CD4 (CD4 molecule)
Diseases named in the same sentence as CD4 in open-access papers (continued):
Sharing a sentence is not in itself a finding about the gene and the disease.
infection (continued). "In monocytes, rapid anti-HIV treatment minimally restored DNA methylation changes associated with infection and unexpectedly had no impact in CD4+ T cells." (PMID 34388205, 2021). "Three studies explored infection with the commensal fungus Candida albicans and showed that Candida albicans can generate long-lived protective CD4+ TRMs in the skin; in particular, the CD4+ CD69+ TRM-like T cells showed increased effector function in response to Candida albicans." (PMID 34445713, 2021). "In addition, the percentage of IL-2+ CD4+ T cells upon anti-CD3 stimulation was decreased compared to day 0 or day four post-infection." (PMID 34869064, 2021). "In addition, we found that phosphorylation of CD3ζ (Tyr83), ZAP70 (Tyr319), and STAT1 (Ser727), as well as the expression of T-bet, was reduced in lung CD4+ T cells of CD4–TREM-2 KO mice upon MHV-A59 infection." (PMID 34878838, 2021). "While the majority of CD4+ T cells die following an infection, a subset survives as memory T cells." (PMID 34299120, 2021). "CD169+ macrophages did not get infected but rather promoted trans-infection of susceptible lymphocytes such as innate-like B1-a cells and CD4+ T cells during the first round of infection." (PMID 34223819, 2021). "It mediates the generation of Ft-specific, gamma interferon (IFN-γ)-secreting, effector memory CD4+ T cells during infection, thus further elucidating the immunological mechanisms involved in enhanced immune protection utilizing this novel mucosal vaccine platform." (PMID 34204226, 2021). "Additionally, immunization with centrin-deleted L. donovani resulted in CD200/CD200R downregulation and consequently suppression of IL-10-producing CD4+ T cells and more Th1 cells compared to WT infection." (PMID 33776999, 2021). "Nevertheless, further investigation will be necessary to demonstrate whether STING signaling modulates NK and CD4+ T cells during infection." (PMID 35095849, 2021). "By contrast, the population of terminal effector CD4+ T-cells in infected mice decreased in the blood and spleen between 30 and 60 days of infection, perhaps as a result of a shorter half-life or a change in cell maturation towards the effector memory phenotype." (PMID 34685494, 2021). "CD4+ T cells have also been identified as important targets for gene therapies targeting HIV, which selectively infects CD4+ T cells and CD4+ myeloid cells after infection and establishes lifelong infections via integration of its genome into the host chromosome." (PMID 33892762, 2021). "However, surprisingly and contrary to primary infection, where CD4 T cells are the only cells capable of controlling the infection, CD8 TRM cells seem to be superior in contributing to local protection compared to memory CD4 T cells in the SG." (PMID 34959486, 2021). "As expected, the frequency of GATA3+ CD4+ T cells also increased with infection." (PMID 34237106, 2021). "Although we had previously reported that C. neoformans Δsgl1 conferred complete protection in CD4-deficient mice, we have now uncovered these mice do not clear the mutant prior to WT infection." (PMID 34568097, 2021). "Similarly, there was a significant decrease in cellular immunity from 6 to 12 months post-infection measured by ELISpot, even though 80% of participants developed measurable CoV-2-specific CD4+T-cells indicative of long-term memory." (PMID 34362088, 2021). "HIV-1 induces rapid genome-wide transcriptome changes following infection of primary CD4+ T cells." (PMID 34154423, 2021). "We also investigated whether pre-incubating CD4+ T cells with pEVs before infection with HIV LAI virus can impact the expression of miR-139-5p." (PMID 34249000, 2021). "IL-21 can also promote B cell responses, the development of Th17 CD4+ T cells, and Tfh CD4+ T cells, which may assist in the resolution of inflammation and the infection." (PMID 34696381, 2021).
infection (continued). "Since L. major infection in mice that resolve the disease is associated with a CD4 Th1 response, we predicted that there might be an increase in IFN-γ from ILCs early after infection." (PMID 34699567, 2021). "During the infection cycle, HIV-1 must overcome several cytoplasmic barriers associated with the innate immune response, even in cells permissive to infection (e.g., CD4+ T cells and macrophages)." (PMID 34572027, 2021). "The resistance of PBMCs from LVLs to infection could be due to many factors, including resistance to infection of CD4+ and/or CD8+ T-cell anti-HIV activity." (PMID 34122382, 2021). "The rapid and essential provision of IL-10 by conventional CD4 T cells raised the possibility that Plasmodium-specific effector CD4 T cells may be rapidly programed to express IL-10 within days of an initial Plasmodium blood-stage infection." (PMID 33529242, 2021). "However, only a slight but significant proliferation of Vβ6+ CD4+ T cells was observed in a study which DCs co-cultured with T lymphocytes from BALB/c spleens in vitro after infection with MMTV (SW), and showed a weak capacity to induce a SAg response." (PMID 35096654, 2021). "CD4+ T cells: The most important peripheral lymphocytes are thought to be CD4+ T cells, which play a central role during anti-infection immunity by orchestrating effective immune responses and influencing both innate and adaptive immune cells via cytokine production and cell-to-cell interactions." (PMID 33532141, 2021). "However, prior DENV immunity did not have any impact on either the transcriptional profile of the CD8 T cells or the capacity of CD4 or CD8 T cells to produce IFN-γ at later stages of infection." (PMID 33679748, 2021). "Immunization with LdCen-/- parasites showed that LdCen-/–infected DCs produce IL-1β, IL-6, and TGF-β to promote the development of Th17 lineage, and upon virulent challenge with wild-type L. donovani (LdWT) infection both CD4 and CD8 T cells produced IL-17, resulting in protection." (PMID 34712235, 2021). "However, we subsequently discovered that full length Bl-Eng2 also harbors a CD4+ T cell antigen starting at amino acid position 35 in the N terminus of the protein that is immune-dominant and protects against experimental infection." (PMID 33735218, 2021). "Furthermore, bacterial flagellin and Toxoplasma specific CD4+ T cell populations in the lamina propria expanded in response to infection in both WT and KO mice." (PMID 34597344, 2021). "Thus, in the current study, RSA59 infection in CD40L-/- mice has served as an efficient model to understand the molecular nexus between CD4+ T cells and microglia/macrophages." (PMID 34898656, 2021). "Other studies identified integration sites in up to 2,661 locations in an in vitro primary CD4 T cell infection model, where integration favored active host transcription units, but with different integration preferences in activated and resting CD4 T cell types." (PMID 33672138, 2021). "Furthermore, current evidence supports the immunogenicity of this protein as well as the ability of spike-containing candidate vaccines to elicit a robust CD4+ T cell response similar to that induced in response to the natural infection." (PMID 34113347, 2021). "Alternatively, HIV-1 may differentially regulate cellular metabolism of target cells to propagate cellular infection and establish viral latency in CD4 T cells." (PMID 34017335, 2021). "The proportion of men who experienced an immunological progression event (i.e., CD4+ T cell count < 350 cells/μL) within 2 years post-infection in the present study was 63%, which is higher than that reported in studies conducted in South West Africa (55%) and South Africa (44%)." (PMID 34367176, 2021).
infection (continued). "We demonstrated that vaccination induces responses that are at least comparable to those induced after infection when measured by either cytokine production at time points beyond the acute peak response or the frequency of SARS-CoV-2-specific central memory CD4+ T-cells." (PMID 34960185, 2021). "Similarly, CD16-CD56- NK cells were also associated with loss of CD29hi CD4+ T cells and reduced absolute CD4+ T cells during infection." (PMID 34721397, 2021). "Taken together, these data revealed that, although HIV infection led to the loss of CD4+ T cells, it resulted in an increase of a unique population of PD-1hiIFN-γ+AREG+FOXP3+ cells that survived the infection and might contribute to immune dysfunction." (PMID 34446704, 2021). "CSF CD4+ T cells were predominantly of a central memory phenotype (median ~65%) with limited effector memory cells (median <10%), and the memory subset composition was unaltered throughout acute infection." (PMID 34874976, 2021). "It is not yet possible to predict whether the low inhibitory effect of IFN-β on newborn CD4+ T cells would be protective or detrimental for disease progression during infection in vivo." (PMID 33912177, 2021). "The greater response of CD4+ T lymphocytes compared to CD8+ lymphocytes is consistent with the findings of another report that analysed the response six to eight months after infection." (PMID 34578848, 2021). "Resulting productive infection of CD4+ T cells or macrophages was then quantified." (PMID 35222352, 2021). "The first step in infection is binding of surface gp120 to CD4." (PMID 34696319, 2021). "Following acute infection, there is an asymptomatic phase with some CD4+ T cell recovery and a decline of viral RNA, however, later developing into a continuous decline of CD4+ T cells and an increase of viral RNA, indicating the chronic phase of infection." (PMID 33451365, 2021). "Together, these features could potentially explain the observed ability of CAF01-induced CD4 T cells to resist infection-driven T cell differentiation, which will be an important research topic of the future." (PMID 33879592, 2021). "We next determined whether there were any phenotypic differences between the vaccine-induced spike-specific CD4+ T cells from the infection-naïve vs. convalescent individuals." (PMID 34636722, 2021). "To further understand the mechanisms of viable NMII bacteria-induced protective immunity, we examined if B cell, T cell, CD4+ T cell, or CD8+ T cell deficiency in mice will significantly affect the ability of viable NMII bacteria to confer protection against virulent NMI infection." (PMID 34795669, 2021). "Our data showed that memory CD4+ T cells represented productively infected cells, which contained abundant viral RNA and DNA, with an equivalent distribution of viral reservoir size in systemic and lymphoid compartments in primary infection." (PMID 34960667, 2021). "However, a subsequent challenge with high-dose SIVmac251 resulted in an infection in all animals although the acute phase of infection demonstrated a more than two-fold reduction in viral replication and protection from CD4+ T-cell depletion." (PMID 34198789, 2021). "As discussed in the context of the infection model, TRPM2 deficiency in cells other than T cells could mask an altered CD4+ T-cells response." (PMID 35095852, 2021). "In contrast to rag1-/-, CD4 genomically deficient mice (cd4-/-) showed similar densities of CD45+ cells and parasites spreading all over the ME and Arc as compared to those in WT mice early after infection." (PMID 34587172, 2021). "A comparison of the immune responses after co-administration of either BCG + H65 or BCG + H107 showed that BCG + H107 induced a much higher proportion of less-differentiated CD4 Th1 cells that accumulated at the site of infection and persisted post Mtb challenge." (PMID 34795205, 2021).
infection (continued). "Interestingly, besides the Th1-related chemokine receptor CXCR3, other chemokine receptors were also found on SG-resident CD4 T cells, in particular during later stages of infection." (PMID 34959486, 2021). "In contrast to our results, the authors observed a significant increase in the production of IFN-γ in the lymph nodes, as well as in the number of specific CD4 T lymphocytes producing IFN-γ at the site of infection, along with a decrease in the production of IL-10." (PMID 34247195, 2021). "Interestingly, when HIV-1 is produced from CD44-expressing cells including PBMCs and hence incorporates CD44, cell-free infection of this HIV-1 is prevented by HA on CD44-expressing target CD4+ T cells at the step of virus attachment." (PMID 34696365, 2021). "We show that, instead of CD4+ T-cell tolerance, priming with optimal signal 1 alone induced almost exclusively a highly functional Th1 effector and memory response compared with mixed Th responses induced by infection or standard immunization." (PMID 32313208, 2021). "Thus, the results implicate that CD4+ T cells significantly express CD40L in the brain upon RSA59 infection." (PMID 34898656, 2021). "To investigate mechanisms involved in establishing both central and effector memory, we analysed Ag-specific TM cells soon after they had formed, 7 days after infection with Lm-2W1S, and separated 2W1S-specific CD4 T cells into CXCR5-ve Tem and CXCR5+ve Tcm cells." (PMID 34108962, 2021). "Replication-inactive CD4+ T cell infection, indicated by unspliced viral RNA in the absence of spliced viral RNA, was even more prevalent, present in CSF of >50% macaques and human CSF at ~10-fold higher frequency than productive infection." (PMID 34874976, 2021). "Hence, we used a recombinant L. monocytogenes strain expressing chicken ovalbumin (LM-OVA) infection model to investigate the USP12 knockdown effects on the CD4+ T cell phenotype." (PMID 33941870, 2021). "In addition, our study showed that transcript abundance of cd4 (Th1 response), cd209 (innate immune response), ccr7 (Th2), and il1b (inflammation) were suppressed during the infection with sea lice alone." (PMID 35046944, 2021). "To further determine whether this CD2-mediated inhibition of HIV-1 early infection steps can be alleviated by lymphatic cytokines, we cultured resting CD4 T cells in IL-2 or IL-7 for 3 days and then latently infected cells with HIV-1." (PMID 34765923, 2021). "In addition to stimulated PBMCs, we also demonstrated infection in trans of FACS sorted CD4+ T lymphocyte subsets expressing co-receptors CCR5 and CXCR4." (PMID 33816339, 2021). "Importantly, these CD4+ T cells maintained their vasculature phenotype and were unable to control infection, even after adoptive transfer into low IL-10 settings." (PMID 34554927, 2021). "In addition, the Omp28 subunit vaccine increased resistance against the B. abortus challenge by inducing a CD4+ Th1 response, that protects against infection, but at a lower level than live attenuated vaccines." (PMID 34992597, 2021). "Overall, it appears that PZQ treatment after infection normalizes serum and tissue responses to ensure a continued immunopathological response to newly deposited parasite eggs while reducing the CD4+ T cell specific tissue responses instrumental in the host granulomatous responses." (PMID 34956183, 2021). "A study on 21 KTR showed that approximately 57% of them presented detectable SARS-CoV-2-specific cell-mediated immunity 6 months after infection (more often CD4+ T cell than CD8+ T cell response), as determined by flow cytometry and IFN-γ FluoroSpot (Mabtech) assay." (PMID 34768356, 2021). "In contrast, CD4 T-cells declined in the colonic mucosa in both groups during acute infection and cART partially restored these cell levels consistently between the two infection groups." (PMID 34452474, 2021).
infection (continued). "In CD4 T cells, HIV reservoirs may be established due to either direct infection of activated memory T cells or progression of infected naïve or effector CD4+ T cells to a memory/resting T cell phenotype." (PMID 33672138, 2021). "CD4+ T helper 1 (Th1) cells are critical for protective immunity against the vector transmitted intracellular parasite Leishmania major, which targets dermal phagocytes as host cells for infection and replication resulting in cutaneous leishmaniasis." (PMID 34543348, 2021). "Therefore, we have studied the CD73+ subset of memory CD4+ T cells in during PHI, their susceptibility to HIV infection in vivo, and the effect of commencing antiretroviral therapy (ART) at that stage of infection, versus late in infection." (PMID 33477692, 2021). "As well, proinflammatory cytokines secreted shortly after infection may activate macrophages and enhance the phagocytosis of infected CD4+ T cells in proximity in vivo." (PMID 34425695, 2021). "Importantly, IL-10 exerted quantitatively stronger regulatory effects on innate and CD4+ T cell responses during primary and secondary infections, respectively." (PMID 34414129, 2021). "Furthermore, in another study, higher percentages of γδ T and B lymphocytes and a decline in CD4+ were detected in tissues of infected sheep during early Map experimental infection." (PMID 35071374, 2021). "However, the level of CD8+ T cell response reduced to almost half as compared to CD4+ after 6 months of infection." (PMID 35250966, 2021). "PCIF1 degradation was also observed in primary CD4+ T cells on days 2 and 3 post-infection." (PMID 34545078, 2021). "Au moment du diagnostic de l'infection VIH, 34,5% (142/411) avaient des infections opportunistes (tuberculose, mycoses, pneumocystose) et 63,5% (261/411) étaient au stade d'immunodépression sévère avec un taux de lymphocytes T CD4 < 200/ml." (PMID 35686172, 2021). "However, during murine cytomegalovirus (MCMV) infection in the salivary glands (SGs), CD4 T cells exhibit direct antiviral effector functions to control the infection." (PMID 34959486, 2021). "In parallel, dendritic cells (DCs) at sites of infection or vaccination capture antigens, migrate to draining lymph nodes and present peptides derived from antigens to CD4+ T cells, thereby activating and driving differentiation of peptide-specific pre-follicular helper T (TFH) cells." (PMID 33562203, 2021). "We assume that in the population of infected macrophages there is an additional death related to infection and due to removal by CD4 T + response cells at a rate km and γm, respectively, so that the lifespan in the population of infected macrophages is 1/(km + μφ + γmT1)." (PMID 34868347, 2021). "However, later studies demonstrated that IL-27 also exhibits anti-inflammatory function through inhibition of CD4+ T cell activation, preventing immunopathology during infection with Toxoplasma gondii, Trypanosoma cruzi, and Mycobacterium tuberculosis." (PMID 33593983, 2021). "Non-susceptible CD4+ T cells that were not CCR5-edited upregulate CCR5 in the presence of infection and replenish the susceptible pool at rate ω4." (PMID 33432929, 2021). "Patients with severe infection had lower levels of CD4+, CD19+, and CD146+ EVs than HD." (PMID 33925492, 2021). "In particular, we wanted to determine whether the increase in T-cells during UgCl223 infection was attributable to either CD4 or CD8 T-cells." (PMID 35186781, 2021). "Further studies examining the plasticity of antigen-specific CD4+ T cells could determine whether their heterogeneity is similarly or differentially influenced by infection type and tissue environment." (PMID 33458613, 2021). "The authors first found that NK cells were the main source of IL-10 (mRNA) at 14 days post-infection with L. donovani by analyzing the purified leucocyte population from the spleen of infected mice, whereas T CD4+ and NK cells were the main sources of IL-10 production at 28 days post-infection." (PMID 35053151, 2021).